LGALS9 (galectin 9)
Diseases named in the same sentence as LGALS9 in open-access papers (continued):
Sharing a sentence is not in itself a finding about the gene and the disease.
breast carcinoma (continued). "Furthermore, PD-L1, CD112, TNFRSF14, TNFSF4, TNFSF18, CD48, and LGALS9 were analyzed for abnormal expression patterns in breast carcinomas." (PMID 34545132, 2021). "Interestingly, it has been previously reported that galectin-9 demonstrates anti-metastatic potential in breast cancer." (PMID 31354733, 2019). "Therefore, the aim of our work was to investigate the biochemical activity of the Tim-3-galectin-9 pathway in human breast cancer and its possible role in suppressing cytotoxic T cell activity." (PMID 31354733, 2019). "Indeed, in breast cancer low galectin-9 expression was a better predictor of distant metastasis compared to lymph node status." (PMID 25259711, 2014). "Additionally, NK cells interacting with galectin-9 on the breast cancer cell surface may release interferon gamma (IFN-γ) in response which could activate cytotoxic lymphoid cells located in the area of the tumor microenvironment." (PMID 31354733, 2019). "In many solid tumors and lymphohematopoietic neoplasms, TIM3/Galectin-9 pathway is closely related to CD8+TILs exhaustion, tumor immune evasion, and poor prognosis, such as breast cancer, glioma, and acute myeloid leukemia." (PMID 38369502, 2024). "The results showed that in breast cancer, GPS1 expression was positively correlated with LAG3, PVRL2, and LGALS9, and negatively correlated with CD274 and HAVCR2, but not with CTLA4 and PDCD1." (PMID 38289496, 2024). "TIM-3, galectin-9, LAG-3 and PD-L2 are expressed in patient-derived breast cancer tissues and are continuously expressed and secreted by different breast cancer-based HTM." (PMID 37174080, 2023). "Breast cancer cells expressing CD47, an immune checkpoint molecule that interacts with macrophages expressing LGALS9, were reported to correlate with poor clinical outcomes." (PMID 36148946, 2022). "In mouse mammary tumors treated with paclitaxel, aTim-3 mAbs act in Tim-3+ tumor-infiltrating cDCs to promote CXCL9-mediated recruitment of CD8+ T cells in a galectin-9–dependent fashion." (PMID 35316223, 2022). "They reported higher expression of both galectin-9 and TIM-3 in breast cancer tissues compared to healthy breast tissues of the same patients by demonstrating the colocalization of these proteins in breast tumors." (PMID 33823818, 2021). "In breast cancer, in vitro studies showed TIM3 expression in cancer cells that led to apoptosis inhibition, proliferation, invasion, and also T cell inhibition in vitro through galectin-9 secretion." (PMID 40645187, 2025). "Additionally, expression of the LGALS9 gene product, Gal-9, is increased following taxane treatment in TNBC, due to nuclear activation of NF-kB, which is also upregulated in HRD breast cancers." (PMID 37919776, 2023). "Although the mechanisms which enable breast cancer cells-TIM-3+ to escape the immune response are still poorly described, it has been demonstrated that the TIM-3/galectin-9 pathway is able to protect breast carcinoma cells against cytotoxic T-cell-induced death." (PMID 36672332, 2023). "Analysis of a dataset containing 3039 primary breast cancer samples on the R2 Genomics Analysis Platform revealed increased TIM-3, galectin-9 and LAG-3 expression, not only in triple-negative breast cancer but also in the HER2+ and hormone receptor-positive breast cancer subtypes." (PMID 37174080, 2023). "Galectin-9 is heavily involved in immune function and is a negative indicator of metastatic ability in breast cancer." (PMID 34638303, 2021). "Importantly our results indicate that galectin-9 is unlikely to be secreted by breast tumors, since its levels do not increase in patient blood plasma and the studied human breast cancer cell lines were incapable of secreting galectin-9." (PMID 31354733, 2019).
breast carcinoma (continued). "Also, In breast cancer, malignant cells can circumvent host immune responses via various mechanisms of immune evasion, including the upregulation of immune checkpoint ligands such as programmed death ligand 1 (PD-L1), PD-L2, poliovirus receptor (PVR; CD155), and galectin-9 (Gal-9)." (PMID 41550509, 2026).
COVID-19 (55 papers, 2020 to 2025). A disease caused by infection with severe acute respiratory syndrome coronavirus 2. "Among inflammatory markers, interleukin 6 (IL-6), interleukin 1 (IL-1), cytoskeleton-associated protein 4 (CKAP4), and galectin-9 (GAL-9 or Gal-9) had received most attention as the common links between COVID-19 and AD manifestations." (PMID 33078369, 2021). "Similarly, Galectin-9 (Gal-9) has also been implicated in the severity of post-COVID-19 pulmonary fibrosis in SARS-CoV2- infections." (PMID 40729284, 2024). "Moreover, some regulatory and tissue repair-associated genes (CD163, IL1R2, AREG, HAVCR2 (encoding TIM-3), and its ligand LGALS9) and pathways (TIM-3/Gal-9 pathway) were found up-regulated in progressive COVID-19 patients." (PMID 37795081, 2023). "LGALS9, the gene encoding Galactin 9, was identified as a target in both experiments, and has been implicated in the severe cytokine response associated with COVID-19." (PMID 35698050, 2022). "To ascertain if biomarkers associated with the Galectin-9/Tim-3 signalling pathway were increased in COVID-19 compared with healthy controls, and could distinguish between IMV and NIMV patients, we measured the concentration of both molecules for the three groups." (PMID 35327637, 2022). "The LGALS9 protein has already been described as a potential biomarker for many diseases, including COVID-19, and is highly expressed in hospitalized patients." (PMID 40877796, 2025). "It is found that plasma Galectin-9 has positive correlation with elevated proinflammatory cytokines and chemokines in COVID-19 patients." (PMID 38686388, 2024). "Of importance, this study provides a comprehensive analysis of circulatory immune factors governing the COVID-19 pathology, and identifies key roles of sCD40, sTIM-1, and Galectin-9 in predicting mortality." (PMID 39376569, 2024). "While sCD40L showed similar increased levels among severe and moderate cases, Galectin-9 was specifically elevated in the serum of severe COVID-19 subjects (p < 0.0001)." (PMID 39376569, 2024). "With our own findings coinciding with the current literature, LGALS9, LAMP3, PRSS8 and AGRN prove to be potential biomarkers of health risk in COVID-19 patients, both individually and collectively." (PMID 39334929, 2024). "Researchers have further confirmed the overexpression of proinflammatory molecules in immune cells from COVID-19 patients once treated with Galectin-9 in vitro experiments." (PMID 38686388, 2024). "CD40 ligand and galectin-9 were both distinctly increased in patients with COVID-19 (i.e. P<0·0001 for COVID-19 versus CAP-other)." (PMID 35660785, 2022). "The angiotensin-converting enzyme 2 (ACE2) receptors and proinflammatory markers such as IL-1 and galectin-9 are common links with respect to COVID-19 and AD." (PMID 35723340, 2022). "The rising of GDF15, galectin-9 and C3a in COVID-19 patients reflect intestinal tight junction dysfunction with translocation of intestinal microbes into the circulation with the development of systemic inflammation." (PMID 36140453, 2022). "In this study, we observed massive elevation of plasma Galectin-9 (Gal-9) in COVID-19 patients compared to healthy controls (HCs)." (PMID 33947753, 2021). "The ROC analysis revealed that only Galectin-9 serum levels may yield an AUC value over 0.700, with sCD40 and sCD25 giving significant but moderate predictive values for severe COVID-19." (PMID 39376569, 2024). "Besides, the expression of Galectin-9 was found to be significantly elevated in severe COVID-19 patients compared to convalescent patients and healthy individuals." (PMID 38686388, 2024). "Namely, we found an enrichment of two COVID-19-unique inhibitory interactions between APCs and CD8+ T cells, CTLA4/CD86 and HAVCR2/LGALS9, which may be out of necessity to curb the heightened inflammation present in severe COVID-19." (PMID 36992700, 2023).
COVID-19 (continued). "Furthermore, a case–control study comprising 80 patients with moderate to severe COVID-19 showed that the GDF15 serum level was increased together with increasing levels of galectin-9 and C3a in severely affected patients." (PMID 36140453, 2022). "Galectin-9 was strikingly increased in patients with COVID-19." (PMID 35660785, 2022). "Among those 5 features with significant time association, ITIH3 and LGALS9 levels appear elevated near symptom onset in severe COVID-19 but decline precipitously thereafter, unlike more stable trajectories in mild and moderate patients." (PMID 35839768, 2022). "COVID-19 and AD share common links with respect to angiotensin-converting enzyme 2 (ACE2) receptors and pro-inflammatory markers such as interleukin-1 (IL-1), IL-6, cytoskeleton-associated protein 4 (CKAP4), galectin-9 (GAL-9 or Gal-9), and APOE4 allele." (PMID 33078369, 2021). "Furthermore, and highlighting the translational relevance of our findings, galectin-9 plasma levels have been shown to correlate with elevated cytokines in COVID-19 patients and addition of recombinant galectin-9 induced IL-6 and TNFα secretion in those patients." (PMID 37755527, 2023). "In conclusion, our study demonstrates that LGALS9, LAMP3, PRSS8 and AGRN are highly significant, differentially regulated plasma proteins found in hospitalised COVID-19 patients." (PMID 39334929, 2024). "LGALS3 or LGALS9 bound to these receptors, and downregulated CD8+ T proliferation and cell function in severe/critical COVID-19 patients." (PMID 37628961, 2023). "Significantly higher levels of galectin-3, galectin-9, IL-1β, IL-1Ra, IL-10, IFN-α2, IL-6, IL-18, and TNF-α were observed in severe COVID-19 and active AOSD patients compared with HC (all p<0.001)." (PMID 34367188, 2021). "Taken together, the increase of Galectin-9 is essential in intestinal barrier damage after spike RBD-Fc stimulation, which might provide novel stratifies for GI symptoms in COVID-19 patients." (PMID 38686388, 2024). "FSTL3 has been implicated as a marker of COVID-19—CVD complications; however, no SNPs were found to be significantly correlated with hospitalisation for LGALS9, LAMP3, PRSS8 or AGRN." (PMID 39334929, 2024). "Furthermore, increased galectin levels, and in particular galectin-9 levels, were observed upon viral infections to dengue, influenza, HIV, hepatitis B and C as well as COVID-19 as compared to healthy controls." (PMID 36142892, 2022). "Moreover, we observed a substantial increase in the frequency of PD-1, TIM-3, 2B4, VISTA, CD160, CD39, Galectin-9 (Gla-9), and TIGIT expressing T cells in COVID-19 patients." (PMID 35284964, 2022). "However, galectin-9 plasma levels also correlated with pro-inflammatory mediator secretion (IL-6, TNFα, CXCL10) in dengue and COVID-19 infected patients." (PMID 36142892, 2022). "Immune checkpoint markers showed distinctive patterns in viral and non-viral CAP, with highly elevated levels of Galectin-9 in COVID-19." (PMID 35660785, 2022). "Among Galectins, increased expression of LGALS9 elicited by SARS-CoV-2 infection correlate with that observed during the HIV-1 infection which was reported to mediate T-cell inflammation and exhaustion as is the case with COVID-19." (PMID 33435561, 2021). "While other studies demonstrate that regulation levels of LGALS9 are distinguishable between healthy controls and COVID-19-positive patients, we demonstrate that LGALS9 levels are not only associated with COVID-19 but also the severity of the disease according to patient hospitalisation." (PMID 39334929, 2024). "Our results also coincide with these published findings and show that LGALS9, LAMP3 and PRSS8 are more expressed in hospitalised COVID-19 patients compared to non-hospitalised ones and demonstrated its utility as a predictive biomarker of health risk." (PMID 39334929, 2024).
COVID-19 (continued). "In this cross-sectional study, plasma levels of galectin-3, galectin-9, and soluble TIM-3 (sTIM-3) were determined by ELISA in 55 COVID-19 patients (31 non-severe and 24 severe), 23 active AOSD patients, and 31 healthy controls (HC)." (PMID 34367188, 2021).
glioma (49 papers, 2020 to 2026). A benign or malignant brain and spinal cord tumor that arises from glial cells (astrocytes, oligodendrocytes, ependymal cells). "We further analyzed the prognostic value of LGALS9 expression across cancer types and identified significant associations of high levels of LGALS9 with shorter overall survival for renal cell carcinoma and glioma patients." (PMID 40775219, 2025). "PTEN deficiency induces galectin-9 secretion, which drives M2 macrophage polarization and therefore is associated with angiogenesis and glioma progression." (PMID 38214828, 2024). "A recent study investigated the expression of Tim-3 and galectin-9 in glioma tissues and showed that there is an association between the expression of these immune checkpoint receptors and the malignancy of gliomas." (PMID 34305910, 2021). "Accordingly, mice transplanted with Lgals9-deficient glioma cells showed improved survival, increased activation of mature DCs, and enhanced CD8+ T-cell proliferation and function." (PMID 35008740, 2021). "Within DC-specific and MG-specific interactomes, we identified LGALS9, which encodes Galectin-9, as a key mediator of cell-cell interactions in IDH-wild type (IDH-wt) gliomas." (PMID 41953006, 2026). "Using an ex-vivo primary human microglia (pMG) and patient-derived glioma stem cells (GSCs) co-culture system, we evaluated the functional role of Galectin-9." (PMID 41953006, 2026). "This also explains that both the abundance of tumor-infiltrating myeloid cells and high expression of LGALS9 predict shorter survival of patients with renal cell carcinoma or glioma." (PMID 40775219, 2025). "While blocking of Galectin-9/Tim-3 signaling has been shown to interfere with the polarization of macrophages toward an M2 phenotype, blocking of Galectin-9 in pediatric gliomas should be more closely evaluated." (PMID 38523840, 2024). "After that, we found that 6 immune checkpoints (CD274, CTLA4, LAG3, LGALS9, PDCD1, and PDCD1LG2) were significantly upregulated in the high-glioma-risk group, while RDH5, RDH10 and DHRS3 simultaneously have a substantial positive connection with PDCD1LG2." (PMID 39465792, 2024). "It has been revealed that Galectin-9 expression was correlated with disease progression and lower OS in gliomas." (PMID 37970435, 2023). "In contrast, high expression levels of TIM-3 and its ligand Galectin-9 were observed in glioma samples." (PMID 34956239, 2021). "Compared with other tumor samples, CEBPA and Galectin-9 were most closely correlated in lower-grade glioma (LGG, WHO grades II and III)." (PMID 34956239, 2021). "t-SNE was performed to evaluate CEBPA and Galectin-9 expression levels in glioma cells with different 1p/19q codeletion statuses." (PMID 34956239, 2021). "The results revealed significantly reduced CEBPA and Galectin-9 expression levels in most glioma cells with 1p/19q codeletion." (PMID 34956239, 2021). "Patients with glioma with high galectin 9, PtdSer, and CEACAM1 expression have significantly lower survival rates than patients with low expression of these ligands." (PMID 33800561, 2021). "In glioma, the expression level of LGALS9 can be scored by the immunoreactive score (IRS), which is correlated with the WHO grade, although LGALS9 expression is lower in LGG than in grade IV glioma." (PMID 32903590, 2020). "Spectral cytometry, immunohistochemistry, and Western blotting analyses confirmed the abundant expression of Galectin-9 in glioma-associated MG, but not in tumor cells." (PMID 41953006, 2026). "Indeed, there is a highly significant correlation between the expression of LGALS9 (the gene encoding Gal9) and CD68 (a classical marker of GB macrophages) expression in patient samples from two distinct glioma cohorts." (PMID 40157890, 2025).
glioma (continued). "Among the galectins analysed, LGALS1, LGALS3, and LGALS9 emerged as significantly upregulated in glioblastoma, consistent with prior studies identifying these molecules as key contributors to glioma progression and suggesting multifaceted roles in tumour progression and resistance mechanisms." (PMID 41516291, 2025). "Glioma prognosis was correlated to immune checkpoints LGALS9, PVR, TNFSF9 and ICOSLG." (PMID 40777122, 2025). "The research team found that by blocking Galectin-9 and Tim-3 (immune-checkpoint molecules expressed on T cells and myeloid cells in adult and pediatric glioma TMEs) signaling, led to a reduction of M2 polarization and subsequent impairment in tumor progression." (PMID 38523840, 2024). "Indeed, glioma patients with galectin-9 over-expression have shown significantly shorter overall survival rates, while galectin-9/TIM-3 association mediates glioma development." (PMID 39513882, 2024). "Notably, we also found that 6 immune checkpoints were significantly upregulated in the high-glioma-risk group, including CD274, CTLA4, LAG3, LGALS9, PDCD1, and PDCD1LG2." (PMID 39465792, 2024). "High level of LGALS9 is an indicator of bad prognosis for all stages of glioma It should be noted that LGALS9/TIM3 signaling pathway regulates T cell functions in several different ways such as regulation of apoptosis in CD4+ T cells and functional exhaustion of CD8+ T cells." (PMID 36960410, 2023). "In addition, high galectin-9 expression levels correlate with a shorter overall survival in lower-grade glioma patients." (PMID 35682991, 2022). "Similarly, although weak expression of galectin-9 was detected in healthy brains, there was a significant increase in its expression in tumor biopsies, especially in grade IV gliomas." (PMID 35008740, 2021). "As the most important transcriptional regulator of Galectin-9 in gliomas, the expression level of CCAAT enhancer-binding protein alpha in samples with 1p/19q codeletion was significantly decreased, which led to the downregulation of the immune checkpoints Galectin-9 and TIM-3." (PMID 34956239, 2021). "To further explore the specific molecular mechanism of this phenomenon, we assessed four transcription factors of Galectin-9 (AR, CEBPA, CEBPB, and TFAP2C) and found that CEBPA on chromosome 19q played a leading role in the transcriptional regulation of Galectin-9 in gliomas." (PMID 34956239, 2021). "Among them, CEBPA played a key role in the regulation of Galectin-9 expression in gliomas." (PMID 34956239, 2021). "In gliomas, galectin-9 inhibits antitumor immune responses, thus favoring tumor progression." (PMID 35008740, 2021). "However, Tim-3 and galectin-9 were highly expressed in TILs and glioma tissues." (PMID 34305910, 2021). "Thus, we hypothesized that 1p/19q codeletion may change the immune microenvironment of glioma by affecting TIM-3 or Galectin-9 expression levels." (PMID 34956239, 2021). "Myeloid/microglial cells can communicate with MAN1C1-expressing glioma cells via signals produced (SPP1, GRN, PSAP, HBEGF, LGALS9, WNT5A)." (PMID 39333557, 2024). "To determine the expression pattern of the TIM3 ligands, galectin 9, PtdSer, CEACAM1, and HMGB1 in gliomas, we examined the RNA-sequencing data of gliomas from GlioVis data portal for the visualization and analysis of brain tumor expression datasets." (PMID 33800561, 2021). "In gliomas, 1p/19q codeletion can promote the antitumor immune response by downregulating the expression levels of the immune checkpoint TIM-3 and its ligand Galectin-9." (PMID 34956239, 2021). "Compared to WHO grade II and grade III glioma, GBM (grade IV) had the highest galectin 9, PtdSer and CEACAM1 expression." (PMID 33800561, 2021). "Given that CD86, LGALS9, and TGFB1 play immunosuppressive roles in glioma, we further investigated the expressing relationship between C1RL and these immunosuppressive genes." (PMID 32993564, 2020).